ENSG00000310184 (novel transcript)
Gene: Long non-coding RNA gene on chromosome 8 (5,123,299 to 5,130,101, forward strand). Ensembl gene ENSG00000310184.
Gene Ontology:
Biological process: RNA processing
Cellular component: nucleolus